SNX15 (sorting nexin 15)
Description:
May be involved in several stages of intracellular trafficking. Overexpression of SNX15 disrupts the normal trafficking of proteins from the plasma membrane to recycling endosomes or the TGN.
Synonyms: HSAF001435
Tractability: Antibody: UniProt places it where antibodies can reach, with high confidence; its Gene Ontology location is reachable by antibodies, with high confidence. PROTAC: ubiquitination databases record sites on it; its protein half-life has been measured.
Gene: Protein-coding gene on chromosome 11 (65,027,437 to 65,040,572, forward strand). Ensembl gene ENSG00000110025.
Subcellular location: Cytoplasm; Membrane; Cytoplasmic vesicle membrane
Subcellular location (Human Protein Atlas): Cytosol; Nucleoli; Plasma membrane; Vesicles
Gene Ontology:
Molecular function: protein binding; phosphatidylinositol binding
Biological process: intracellular protein transport
Cellular component: cytosol; membrane; cytoplasm; cytoplasmic vesicle membrane
Genetic constraint (gnomAD): Loss-of-function variants: 30 observed, 36.43 expected, observed/expected ratio (o/e) 0.82, 90% interval 0.62 to 1.12. The upper end of that interval is the gene's LOEUF score, 1.12, which puts it in group 4 of 6, group 1 being the genes least tolerant of losing a copy. Missense variants: 398 observed, 444.65 expected, observed/expected ratio (o/e) 0.9, 90% interval 0.82 to 0.97. Synonymous variants: 183 observed, 186.59 expected, observed/expected ratio (o/e) 0.98, 90% interval 0.87 to 1.11.
Homologues: Orthologues: chimpanzee SNX15 (99% identical), macaque SNX15 (98% identical), pig SNX15 (92% identical), guinea pig SNX15 (90% identical), mouse Snx15 (87% identical), dog SNX15 (83% identical), rat Snx15 (77% identical), rabbit SNX15 (56% identical), tropical clawed frog snx15 (47% identical), zebrafish snx15 (45% identical). Paralogues in human: RPS6KC1 (36% identical), RPS6KL1 (12% identical).
Diseases named in the same sentence as SNX15 in open-access papers:
SNX15 is named in the same sentence as 6 diseases in open-access papers, as found by Europe PMC text mining. Sharing a sentence is not in itself a finding about the gene and the disease. The quoted sentences say what the papers report.
Alzheimer disease (1 paper, 2022). A progressive, neurodegenerative disease characterized by loss of function and death of nerve cells in several areas of the brain leading to loss of cognitive function such as memory and language. "Interestingly, three of these genes (EPN2, SNX15, and DGCR8) have previously been associated with hippocampal functioning and processes linked to the development of Alzheimer’s disease (AD)." (PMID 35933470, 2022).
cholangiocarcinoma (1 paper, 2021). A carcinoma that arises from the intrahepatic biliary tree (intrahepatic cholangiocarcinoma) or from the junction, or adjacent to the junction, of the right and left hepatic ducts (hilar cholangiocarcinoma). "In conclusion, the results of the present study suggest that the cholangiocarcinoma (CHOL)-hub genes (SNX15, ATP2A1, PDCD10, BET1, and HMGA2) can be used as biomarkers of tumor progression, metastasis, therapy outcome, and poor prognoses of CHOL." (PMID 34831096, 2021).
mammary adenocarcinoma (1 paper, 2021). "SNX15 is a regulator of intracellular protein trafficking consisting of endocytosis, endosomal sorting, and endosomal signaling and was associated with mammary adenocarcinoma metastases to the lungs." (PMID 34831096, 2021).
tumor (2 papers, 2021 to 2023). "However, we compared expression profiles between tumor grades and found that SNX15, ATP2A1, PDCD10, BET1, and HMGA2 expressions were significantly (all p < 0.05) associated with tumor stages." (PMID 34831096, 2021). "Using Spearman's rank correlation analysis, we explored the existence of a correlation between anti‐FIRΔexon2, anti‐CFAP70, anti‐KARS, anti‐SNX15, or anti‐SOHLH1 Abs and clinically used tumor markers." (PMID 37964630, 2023). "Suggestively, our results indicated that SNX15, ATP2A1, PDCD10, BET1, and HMGA2 could serve as a biomarker signature of tumor progression and metastasis in CHOL patients." (PMID 34831096, 2021).
SNX15 also shares sentences with these, for which no sentence is quoted: cancer (1 paper); infection (1).